UCP2 (uncoupling protein 2)
Diseases named in the same sentence as UCP2 in open-access papers (continued):
Sharing a sentence is not in itself a finding about the gene and the disease.
ischemia (21 papers, 2006 to 2025). A hypoperfusion of the BLOOD through an organ or tissue caused by a PATHOLOGIC CONSTRICTION or obstruction of its BLOOD VESSELS, or an absence of BLOOD CIRCULATION. "Administration of resveratrol, a natural compound found in certain foods, beverages, and supplements, has demonstrated neuroprotection against ischemia in rats via the SIRT1 uncoupling protein 2 (SIRT1-UCP2) pathway." (PMID 38992073, 2024). "Collectively, these studies show that short periods of ischemia and reperfusion as they are used for conditioning increase UCP2 protein expression." (PMID 37047436, 2023). "Compared with the WT+HG group, UCP2-/- +HG group had more severe neurological deficit scores after ischemia/reperfusion (p<0.05)." (PMID 33061796, 2020). "Overall, the Opa1 and Mfn2 levels were intended to be lower in hyperglycemic ischemia than in normoglycemic ischemia and deletion of UCP2 affected these fusion markers in normoglycemic ischemic mice." (PMID 33061796, 2020). "The objective of this study was to explore the impact of UCP2 deletion on mitochondrial dynamic balance in ischemia and reperfusion injury under both normo-and hyperglycemic conditions." (PMID 33061796, 2020). "Pre-treatment with resveratrol has been demonstrated to have neuroprotective effects following ischemia via the SIRT 1 uncoupling protein 2 pathway (SIRT1-UCP2)." (PMID 30037107, 2018). "Pioglitazone has been shown to protect the heart by upregulating expression of UCP2 to reduce ROS production during ischemia-reperfusion injury." (PMID 29182629, 2017). "Our results suggest that UCP2 protects against ischemia-induced brain damage by activating cell survival signals." (PMID 22348126, 2012). "Our studies confirmed previous findings that cerebral ischemia reduces the transcript levels of Bcl-2 and showed that upregulation of UCP2 in transgenic mice ameliorated ischemia-induced Bcl2 suppression." (PMID 22348126, 2012). "In the central nervous system (CNS), UCP2 has been shown to be upregulated by stress signals such as kainate administration, injury or ischemia, and overexpression of UCP2 has been reported to be neuroprotective against oxidative stress in vivo and in vitro." (PMID 22849356, 2012). "Conversely, endogenous protective pathways exist to counteract these detrimental effects induced by ischemia including mitochondria proteins UCP2 and SOD2, which are all regulated by PGC-1α." (PMID 22072942, 2011). "Column 7 indicates that, in a lethal ischemia group, ghrelin increased both the number of surviving neurons and the measured amount of UCP2 mRNA." (PMID 19772611, 2009). "Opposed to increased UCP2 being neuroprotective is a study showing that UCP2 knockout mice were less sensitive to ischemia following cerebral artery occlusion than wildtype mice." (PMID 16968550, 2006). "An induction of UCP2 expression in the brain was also shown in an AMPK-dependent way or ischemia." (PMID 37047436, 2023). "It has been reported that UCP2 could be upregulated by stress, injury or ischemia, and overexpression of UCP2 plays neuroprotective effects against oxidative stress in vivo and in vitro." (PMID 36142731, 2022). "Moreover, deletion of UCP2 altered mitochondrial dynamic balance by tilting the balance towards fission, especially in hyperglycemic animals after being subjected to ischemia and reperfusion." (PMID 33061796, 2020). "Ucp2 and Ucp3 also dissipate the mitochondrial electrical potential, but do so in order to reduce the production of the superoxide radicals at complex I in the setting of ischemia." (PMID 33287280, 2020). "However, our observations suggest that UCP2 modulates cardioprotective effects of Ru360 during ischemia." (PMID 26248074, 2015). "Mice overexpressing UCP2 in the brain had significantly less damage after transient focal ischemia." (PMID 22348126, 2012). "UCP2 decreases the levels of Cdc25a, therefore it may reduce apoptotic cell death induced by ischemia." (PMID 22348126, 2012).
ischemia (continued). "is suppressed by ischemia and its suppression is elevated by UCP2 overexpression." (PMID 22348126, 2012). "The hypothesis we envisaged is that UCP2, which is known to reduce mitochondrial ROS production, would protect the neurons from a lethal ischemia if over-expressed during the appropriate period." (PMID 19772611, 2009). "In addition, the expression of genes related to antioxidants was suppressed in UCP2-knockout mice during cerebral ischemia–reperfusion, which suggests that UCP2 may decrease brain damage by reducing oxidative stress during ischemia–reperfusion." (PMID 28737710, 2017). "Therefore, one might speculate that during ischemia, UCP2 influences cardioprotective implication of MCU inhibition." (PMID 26248074, 2015). "For instance, resveratrol has been shown to mimic the effect of ischemic preconditioning, the most powerful endogenous mechanism of protection against ischemia, via SIRT1/UCP2 activation." (PMID 34201106, 2021). "UCP2 Tg mice had increased protein levels of phospho-Ser AKT 473, Heat Shock Protein 90, Protein Kinase C, MAP Kinase Kinase, and MAP Kinase Kinase 4 compared with wild-type controls after ischemia." (PMID 22348126, 2012). "UCP2 does not affect cell survival in hypoxic cardiomyocytes, but it might modulate cardioprotective effects of Ru360 during ischemia." (PMID 26248074, 2015). "IPC alone (column 3) increased the measured amount of UCP2 mRNA (without significant reduction of the number of surviving neurons), but when it was followed by a lethal ischemia (column 4) the amount of UCP2 mRNA (on day 6) was reduced, though still higher than in the control group." (PMID 19772611, 2009).
metabolic syndrome (21 papers, 2006 to 2024). A cluster of metabolic risk factors for CARDIOVASCULAR DISEASES and TYPE 2 DIABETES MELLITUS. "RSV + QRC increased UCP2 mRNA in control and metabolic syndrome rats, and the elevation was associated with an increase in oleic and linoleic fatty acids." (PMID 33670130, 2021). "It ameliorated dyslipidemia, improved insulin sensitivity, and reversed the expression of UCP2, Nr1H4, and Fiaf." (PMID 38469405, 2024). "We found that in metabolic syndrome rats, the mostly-expressed isoform was UCP2, low levels of UCP3 were present, and UCP1 was undetectable." (PMID 33670130, 2021). "This study provides new evidence concerning associations between genetic variations in the UCP2 and UCP3 genes and serum lipid concentrations as well as indices of abdominal obesity, both being characteristics of the metabolic syndrome." (PMID 19769793, 2009). "In the current study we aimed to investigate the major components of metabolic syndrome in patients with non-alcoholic fatty liver disease (NAFLD) and nutritional intakes according to different genotype of uncoupling protein-2 (UCP2) −866G/A gene polymorphism in these patients." (PMID 27301474, 2016). "Genotyping UCP2 and probably KCNJ11 may help to select the optimal antidiabetic therapy and improve disease prognosis, whereas the MTHFR gene may determine the need to monitor group B vitamin status and the risk of dyslipidemia." (PMID 34289004, 2021). "Ginsenoside Rb1 (Rb1) oral supplementation ameliorated dyslipidemia, improved insulin sensitivity in HFD-induced obese mice, and reversed the expression of uncoupling protein 2 (UCP2), Nuclear receptor subfamily one group H member 4 (Nr1h4), and Fiaf." (PMID 38469405, 2024). "The anti-dyslipidemia effects may be involved in the downregulation of adipogenic and lipogenic genes (C/EBP-α/-β, SREBP1, PPARγ, and FAS) and the upregulation of genes exerting transcriptional roles in lipolysis and β-oxidation (PPARα and UCP2)." (PMID 35326230, 2022). "Our study reveals that expression of UCP2, but not UCP3, is lower in the skeletal muscle of ATX mice, suggesting that ROS production is favoured under dyslipidemia and that oxidative stress is more prone to happen." (PMID 27010651, 2016).
leukemia (20 papers, 2010 to 2024). A malignant (clonal) hematologic disorder, involving hematopoietic stem cells and characterized by the presence of primitive or atypical myeloid or lymphoid cells in the bone marrow and the blood. "The Warburg effect in certain leukaemia cells is linked to UCP2 activation." (PMID 21712825, 2011). "In conclusion, our study demonstrates that UCP2 plays an important role in leukemia cells to allow proper use of glutamine, in particular when the cells have a high energetic dependency on glutaminolysis." (PMID 36275699, 2022). "In contrast, Jurkat leukemia cells, which express low levels of UCP2 and are dependent on glycolytic metabolism, were less metabolically affected by Ucp2 knockdown." (PMID 36499405, 2022). "We report that UCP2 plays a key role in controlling leukemia cell proliferation through glutamine metabolic remodeling." (PMID 36275699, 2022). "Due to this dual dependency, UCP2 appears as an attractive candidate in the metabolic remodeling of T-ALL leukemia cells." (PMID 36275699, 2022). "MSCs, increase leukemia cells’ expression of uncoupling protein 2 (UCP2), a mitochondrial inner membrane protein that dissipates the electrochemical gradient generated by the mitochondrial respiration chain." (PMID 34771483, 2021). "It was demonstrated that the co-culture of leukemia cells with mesenchymal stem cells (MSCs) increased the expression of uncoupling protein 2 (UCP2) in leukemia cells; uncoupling oxidative phosphorylation and decreasing ROS production." (PMID 32211323, 2020). "It has been demonstrated that in leukemia cells, MSCs increase the expression of uncoupling protein 2 (UCP2), a mitochondrial inner membrane protein that short circuits the electrochemical gradient generated by the mitochondrial respiration chain." (PMID 31709192, 2019). "This led to sensitization of drug-resistant leukemia cells to chemotherapeutics, indicating that manipulation of UCP2 glutathionylation status can serve as a therapeutic strategy for cancer treatment." (PMID 29351723, 2018). "UCP2 expression is stimulated by co-culturing of these leukemia cells with bone marrow-derived mesenchymal stromal cells." (PMID 23966948, 2013). "In particular, over-expression of UCP2 has been reported in leukemia as well as in breast, colorectal, ovarian, bladder, esophagus, testicular, kidney, pancreatic, lung, and prostate cancer." (PMID 23966948, 2013). "For instance, genipin-induced inhibition or glutathionylation of UCP2 sensitizes drug-resistant leukemia subclones to chemotherapy with menadione, doxorubicin, or epirubicin." (PMID 23966948, 2013). "As a matter of fact, multi-resistant subclones of leukemia cells show higher UCP2 protein expression, lower ΔΨm, lower radiation induced formation of reactive oxygen species and decreased DNA damage as compared to their parental sensitive cells." (PMID 23966948, 2013). "Our analyses of Oncomine data sets revealed that UCP2 is over-expressed in ovarian, bladder, esophageal, testicular, kidney, colorectal, lung, pancreas and prostate cancers as well as in leukemia." (PMID 21935467, 2011). "Drug resistance is weakened by genipin in MX2 leukaemia cells that have abundant mitochondrial UCP2." (PMID 21712825, 2011). "This was also observed with drug-resistant L1210/DDP leukemia cells which use UCP2 to quench chemotherapy-induced ROS through a proton leak mechanism." (PMID 20967268, 2010). "In fact, UCP2 silencing results in higher rates of activation of apoptotic pathways in leukemia cells transfected with UCP2 siRNA." (PMID 24281083, 2010). "Besides mitochondrial transfer, MSCs stimulate uncoupling protein 2 (UCP2) expression in leukemia cells and induce AML cells chemoresistance." (PMID 37746249, 2023). "Therefore, interfering with UCP2 function can be considered as an interesting strategy to decrease metabolic efficiency and proliferation rate of leukemia cells." (PMID 36275699, 2022).
leukemia (continued). "Thus, while UCP2 silencing decreases cell proliferation in all leukemia cells, it also alters mitochondrial respiration of T-ALL cells relying on glutamine-dependent oxidative metabolism by rewiring their cellular metabolism to glycolysis." (PMID 36275699, 2022). "Thus, while UCP2 silencing decreases cell proliferation in all leukemia cells, it also alters mitochondrial respiration of T-ALL cells relying on oxidative metabolism dependent of glutamine." (PMID 36275699, 2022). "Interestingly, mitochondrial membrane potential reduction was mediated in leukemia cells by an uncoupling protein 2 (UCP2)-dependent mechanism, suggesting that MSCs facilitated the Warburg effect in cancer cells by activating highly conserved mammalian UCPs." (PMID 33330442, 2020). "Interestingly, it has been also reported in leukemia that genipin, an UCP-2 inhibitor, sensitized drug-resistant cells to anthracyclin." (PMID 32545695, 2020). "Thus, in most malignant cells as in early developing colorectal cancer, nonsmall cell lung cancer, leukemia, and pancreatic cancer UCP2 levels are elevated." (PMID 29351723, 2018). "Similarly, the prooxidative state was set up by glutathionylation catalyst diamine selectively deactivating UCP2 in leukemia Mx2 cells." (PMID 29351723, 2018). "This was shown in a study by one of us, which also found that after a low-LET dose of 20 Gy in aerated conditions, resistant subclones of leukemia cells have elevated UCP2 activity, suppressing ROS and subsequent nucDNA damage as measured by 8-oxo-deoxyguanosine." (PMID 26894978, 2016). "Moreover, multi-resistant subclones of leukemia cells reportedly show higher UCP-2 protein expression, lower ∆Ψm, lower radiation induced formation of reactive oxygen species and decreased DNA damage as compared to their parental sensitive cells." (PMID 26304588, 2015). "Furthermore, UCP2 over-expression was found in other cancers, including leukemia, bladder, esophagus, testicular, colorectal, kidney, lung, pancreatic and prostate cancers." (PMID 21935467, 2011). "Furthermore, over-expression of UCP2 was also found in leukemia, ovarian, bladder, esophagus, testicular, colorectal, kidney, pancreatic, lung and prostate tumors." (PMID 21935467, 2011). "Further experiments using different leukemic cell lines and human leukemia samples would be interesting to demonstrate whether the expression of the mitochondrial protein UCP2 could be a good marker to stratify leukemia cells whose oxidative metabolism depends on glutamine." (PMID 36275699, 2022). "Moreover, UCP-2 inhibitors could sensitize drug resistant leukemia cells to chemotherapeutics, suggesting that targeting this oncogenic protein may be a potential strategy for the treatment of chemo-resistance." (PMID 26107945, 2015). "Overexpression of mitochondrial uncoupling protein 2 (UCP2), which results in increased proton leakage from the mitochondria and helps the cells to control ROS, is connected with resistance of drug-resistant leukemia cells to chemotherapeutic drugs." (PMID 39125992, 2024).
pancreatic cancer (18 papers, 2015 to 2026). "Mitochondrial uncoupling protein 2 (UCP2) is a potential target for cancer drug therapy in pancreatic cancer." (PMID 40438494, 2025). "Combining UCP2 with chemotherapeutic agents as an adjuvant strategy shows potential application value, enhancing effectiveness in inhibiting pancreatic cancer." (PMID 39707176, 2024). "The mitochondrial uncoupling protein 2 (UCP2) has potential as a cancer-specific drug target, and thus, we will review the known biology of UCP2 and discuss its potential role in the pathobiology and future therapy of pancreatic cancer." (PMID 38194152, 2024). "Recently, the same team demonstrated in pancreatic cancer cells that UCP2 catalyzes the efflux of mitochondrial aspartate." (PMID 36275699, 2022). "Conversely, UCP2 has been shown to help tumor cells proliferate by inhibiting ROS production 13, 14 and promote pancreatic cancer proliferation." (PMID 33859525, 2021). "In several studies, UCP2 was shown to play an important role in the resistance of pancreatic cancer to chemotherapy." (PMID 33859525, 2021). "For example, increased expression of UCP2 can suppress glucose-stimulated insulin secretion, and inhibition of UCP2 expression was shown to decrease the growth of PaCa44 human pancreatic cancer cells." (PMID 32190174, 2020). "For instance, UCP2 expression was found to reduce superoxide production by gemcitabine to produce a protective effect on pancreatic cancer cells, which was reverted by UCP2 inhibition with genipin." (PMID 35582564, 2019). "The antioxidant effect of UCP2 plays a vital role in the resistance of pancreatic cancer cells to standard chemotherapy." (PMID 26771380, 2016). "Mitochondrial UCP2 has been reported to be over-expressed in pancreatic cancer tissues compared with adjacent normal tissues." (PMID 26771380, 2016). "In pancreatic cancer, inhibition of mitochondrial uncoupling protein 2 (UCP2) by genipin enhances the efficacy of 2-deoxyglucose (2-DG), suggesting that co-targeting the UCP2–PKM2 metabolic axis disrupts mitochondrial bioenergetics and glycolysis simultaneously." (PMID 40842995, 2025). "Given the significant role of UCP2 in the pancreas and pancreatic diseases, this review focuses on the recent research progress regarding the involvement of UCP2 in pancreatic development, pancreatitis, pancreatic endocrine diseases, and pancreatic cancer." (PMID 39707176, 2024). "In models of acute pancreatitis (AP), UCP2 knockdown inhibits the proliferation of pancreatic stellate cells, and modulates macrophage redox responses, impacting the progression of KRAS-associated pancreatic cancer." (PMID 39707176, 2024). "This evidence supports the reasonable hypothesis that MMT may also play a role in pancreatic diseases, particularly in CP and pancreatic cancer, with UCP2 likely influencing this process to some extent." (PMID 39707176, 2024). "Recently, the SLC25A8 protein called mitochondrial uncoupling protein 2 (UCP2), inducing proton leak and involved in the transport of C4 metabolites out of mitochondria, has been demonstrated to support growth of KRAS mutated pancreatic cancer." (PMID 37726810, 2023). "Interestingly, UCP2 sensitized pancreatic cancer cells to the glycolytic inhibitor 2-deoxy-D-glucose, and cell growth inhibition by genipin was reversed in cells transfected with siUCP2." (PMID 35628447, 2022). "Interestingly, overexpression of UCP2 in human pancreatic cancer and glioblastoma cell lines was recently described to repress malignancy by controlling mitochondrial function and redirecting energy production away from glycolysis." (PMID 26148070, 2015).